PMS2 (PMS1 homolog 2, mismatch repair system component)
Diseases named in the same sentence as PMS2 in open-access papers (continued):
Sharing a sentence is not in itself a finding about the gene and the disease.
Lynch syndrome (continued). "Moreover, several studies have reported that Lynch syndrome with germline mutations in MSH6 or PMS2 might not necessarily show MSI-H30,31." (PMID 34625576, 2021). "Universal tumour testing for Lynch syndrome revealed that MSH6 and PMS2 carriers are more frequent than previously recognized." (PMID 33916129, 2021).
Lynch syndrome (continued). "We conducted immunohistochemical analysis of CRC tumors from several rhesus macaques, finding they frequently lack expression of MLH1 and PMS2 proteins, both critical MMR proteins involved in Lynch Syndrome." (PMID 30108684, 2018). "We report 15 novel MSH6 mutations and 1 novel PMS2 mutations in Lynch syndrome families not listed in the Mismatch Repair Genes Variant Database (Memorial University of Newfoundland), the InSIGHT database as a Lynch syndrome mutation or the Leiden Open Variation Database (LOVD)." (PMID 20487569, 2010). "Two cases exhibited MMR deficiency: one showed loss of MLH1 and was clinically diagnosed with Lynch syndrome (germline MLH1: T117M), while the other (a 53-year-old woman) had concurrent loss of MLH1 and PMS2 without detectable germline variants in either gene." (PMID 41463182, 2025).
Lynch syndrome (continued). "Thirty-nine patients (2%) were identified as carriers of a PV in an autosomal dominant clinically actionable hereditary breast and ovarian cancer (HBOC)-related or Lynch syndrome gene, most frequently, BRCA2 (6/39; 15.4%), PALB2 (8/39; 20.5%), CHEK2 (10/39; 25.6%), and PMS2 (5/39; 12.8%)." (PMID 37861889, 2024). "In PMS2‐associated CMMRD, there is often no family history, as Lynch syndrome associated with PMS2 mutations has a relatively low age‐dependent penetrance with a reported mean age of 52 years at presentation." (PMID 36341503, 2023). "MLH3 gene encodes a protein that functions as a heterodimer with other MMR genes, and PMS1 gene encodes a protein that forms a heterodimer with MLH1 and PMS2, products of MMR genes involved in Lynch syndrome (nonpolyposis colorectal cancer, HNPCC)." (PMID 37656691, 2023). "Among the 28 cases showing an MMR-d phenotype, 25 had a combined loss of MLH1 and PMS2 (including 19 SBAs with MLH1 methylation and 6 without MLH1 methylation, one of which was in a confirmed Lynch syndrome patient)." (PMID 32761330, 2021). "Therefore, the use of only two antibodies, anti-PMS2 and anti-MSH6 antibodies, allows the screening of Lynch syndrome to be performed with a sensitivity equivalent to that using four antibodies." (PMID 34185173, 2021). "Using IHC with a two-antibody (MSH6 and PMS2) panel would (assuming that no Lynch syndrome cases were missed) save approximately £15 per patient compared to using the full panel with no change in QALYs." (PMID 32492863, 2020).
Lynch syndrome (continued). "These patients had Cowden syndrome, that had not been diagnosed clinically or PMS2‐Lynch syndrome that was difficult to detect using WES." (PMID 30809968, 2019). "In our cohort, we selected patients with no family history, which largely excludes Lynch syndrome, although CRC caused by PMS2‐mutation with its low penetrance can occur in the absence of family history." (PMID 30809968, 2019). "Initial immunohistochemistry (IHC) analysis was deemed inconclusive for Lynch syndrome due to perceived poor technical quality of PMS2 staining; there was universal absence of PMS2 antibody uptake in tumour and control tissue." (PMID 28381238, 2017). "She had a bi-allelic PMS2 mutation and thus a diagnosis of constitutional mismatch repair deficiency (CMMRD) rather than Lynch syndrome." (PMID 28065618, 2017). "PMS2, a gene responsible for Lynch syndrome, previously referred to as hereditary non-polyposis colorectal cancer, was mutated in this case of granulosa cell tumor." (PMID 28347324, 2017). "Molecular phenotyping identified loss of mismatch-repair protein immunostaining for PMS2, microsatellite instability, a lack of MLH1 promoter methylation, and lack of BRAF mutation suggestive of Lynch syndrome." (PMID 27965933, 2016). "We also found that the pattern of MMR deficiency in early-onset CRC patients is not identical to that for all Lynch syndrome cases, and is characterized by in increased frequency of MSH6 and PMS2 deficiency." (PMID 23049789, 2012). "Therefore, the presence of the BRAF V600E variant in tumor tissue almost excludes the possibility of Lynch syndrome in cases where MMR-IHC reveals loss of expression of both the MLH1 and PMS2 proteins." (PMID 41214301, 2026). "The most common gene affected in CMMRD is PMS2, unlike Lynch syndrome." (PMID 40546517, 2025).
Lynch syndrome (continued). "The double-hit events of mismatch repair genes could result in Lynch syndrome, as described in several studies, but we did not detect double-hit events in PMS2 in our ESCC cohort." (PMID 33889545, 2021). "We found that IHC with a two-antibody (MSH6 and PMS2) panel would detect all 16 (100%) Lynch syndrome cases in the PETALS study, and on the basis of the assumption that it would halve the cost of IHC testing, it would also result in cost saving, costing £1200 per Lynch syndrome case identified." (PMID 32492863, 2020). "Regarding this point, our study suggests that PMS2, which does not contribute greatly to Lynch Syndrome, could be considered a good candidate for evaluation." (PMID 27779110, 2017).